MMP9 (matrix metallopeptidase 9)
Diseases named in the same sentence as MMP9 in open-access papers (continued):
Sharing a sentence is not in itself a finding about the gene and the disease.
infection (continued). "NS-398 treatment prior to infection inhibited total as well as active-MMP-9 secretion implicating the role of KSHV induced COX-2 in regulating MMP-9." (PMID 20169190, 2010). "Cells stimulated with S7565 had a peak MMP9 mRNA production at 48-hr after infection, which was significantly higher (P < 0.05) when compared with stimulations by other MAP isolates." (PMID 16478544, 2006). "After MO infection, the expression of MMP9 in sheep alveolar macrophages decreased, which may affect the remodelling of lung tissue after injury." (PMID 41146353, 2025). "Therefore, we utilized colocalization to determine the site of viral invasion at 72 h post infection using GFAP/MMP-9, neuronal nuclei (NeuN)/MMP-9, and CD31/MMP-9." (PMID 40176142, 2025). "Infection also triggers a significant increase in astrocyte proliferation and a shift towards the A1 astrocyte subtype, which is known to secrete high levels of MMP-9, further exacerbating BBB damage." (PMID 40176142, 2025). "It decreases macrophage-driven pro-inflammatory cytokine and chemokine release—such as TNF-α, IL-1β, IL-6, CXCL-1, CXCL-2, and matrix metalloproteinase-9 (MMP-9)—and attenuates neutrophil infiltration into the lungs, thereby mitigating lung injury and infection." (PMID 41357831, 2025). "Mice of all groups were euthanized on the 6th day post-infection, and the intestine of each was isolated for parasitological, histopathological, and immunohistochemistry evaluation of MMP-9, as well as assessment of cytokines level (IFN-γ and IL-10 gene expressions) via Real-time PCR technique." (PMID 39421828, 2024). "In a previous study, infection with A. cantonensis in mice resulted in increased expression of plasminogen activators and MMP-9, leading to damage to the BBB, degradation of the extracellular matrix (ECM), and infiltration of immune cells, leading to eosinophilic meningitis." (PMID 38922036, 2024). "When V. cholerae was injected alone, mRNA levels of tnfa and il1b incrementally increased throughout infection, mmp9 and cxcl18b levels were highly elevated at 6 hpi before decreasing by 18 hpi, and cxcl8a levels increased by 6 hpi but remained constant through 18 hpi." (PMID 39024393, 2024). "The levels of MMP-9, COX-2 and p-NF-κB were significantly increased and HO-1 levels were moderately increased in the infection groups; however, MMP-9, COX-2 and p-NF-κB levels were significantly decreased and HO-1 levels were significantly increased in the ABZ plus calycosin treatment groups." (PMID 36341547, 2023). "The concentration of active MMP-9 increases with wound severity and infection." (PMID 37313229, 2023). "Importantly, MMP expression associated with chlamydial infection has been shown to be sensitive to IL-17 signaling, with il17-/- mice displaying reduced oviduct expression of MMP2/MMP9 relative to wild-type mice following infection with C. muridarum." (PMID 37265500, 2023). "A body of studies recorded increased MMP-7 and MMP-9 activity in blood circulation when patients were admitted to hospital after being infected with this disease, characterizing the initial phase of the infection." (PMID 37372128, 2023). "Additionally, auraptene-treated MRC-5 cells during HCoV-OC43 infection decreased the MMP-9 mRNA levels which are usually increased due to the infection, as auraptene is a previously reported MMP-9 inhibitor." (PMID 37447286, 2023). "However, similar to the lung following i.n. infection MMP-9 levels trended downward (p<0.24) within the ear of FTT infected mice with LPS preconditioning relative to mock control." (PMID 37883420, 2023). "infection, there was a statistically significant difference in the MMP-9/TIMP-1 ratio." (PMID 35563321, 2022). "It is possible that during infection with H. pylori both ROS and MMP-9-driven apoptosis may be involved in atherogenesis." (PMID 35683034, 2022).
infection (continued). "On the other hand, the inflammation in patients with infection is further amplified via the expression of cytokines triggered by up-regulated matrix metalloproteinase-9 (MMP-9), an inflammatory mediator induced by the synergy between DM and tissue-type plasminogen activator (tPA)." (PMID 36533168, 2022). "An increase in the expression levels of the mmp-9 was evidenced with a peak at 24 h post-infection." (PMID 35328519, 2022). "Additionally, multiple MMPs, including MMP-2, MMP-9 and MMP-14, have been implicated in tissue pathology in the lung mucosa and female genital tract during infection through mediating inflammation and ECM degradation." (PMID 35512020, 2022). "There was evidence of different temporal dynamics in ICUCovid compared to NeuroCovid patients with PPIA, the potent activator of the cytokine storm and MMP-9 inducer, and IL-10, the master regulator of immunity to infection, with the highest levels in ICUCovid patients in the acute phase." (PMID 36591311, 2022). "Furthermore, the observation of focal areas of collagen is present in case 1 and even the absence of expressive focal areas in cases 2 and 3 configured an indication of infection markers to be researched during the work, such as MMP-9 (Metalloproteinase-9)." (PMID 36558877, 2022). "In addition, the induction of BBB permeability and upregulation of MMP-9 during CNS VEEV TC-83 infection are dependent on TLR4." (PMID 33487119, 2021). "While MMP9 levels remain unchanged with infection, levels are enhanced with reported fever." (PMID 34737733, 2021). "The MMP-9/TIMP-1 ratio was greater in the hippocampus of the immunosuppressed Acanthamoeba spp.-infected mice than of the uninfected animals at the beginning of infection." (PMID 33514026, 2021). "Importantly, activation of MMP-9 was induced upon infection with the three different H. pylori strains independently of HpHtrA expression." (PMID 34742300, 2021). "Moreover, during the course of infection, MMP9 was normally expressed in the seminiferous epithelium but then translocated to the interstitial spaces and the basement membrane, which was mainly composed of type IV collagens." (PMID 32302362, 2020). "We hypothesized the serum MMP9 circulating in the body fluid might be the major source of MMP9 in the testis at the early stage of infection, leading to mild leakage of BTB." (PMID 32302362, 2020). "To prove that TIMP-2 could inhibit HCT-116 cells invasion and migration by regulating MMP-9, we had a secondary lentivirus-infection to vary MMP-9 expression." (PMID 31293204, 2019). "On neonatal monocytes CD95L density is reduced upon infection due to lower activity of MMP-9." (PMID 30897723, 2019). "MMP-9 has a major role in tissue degradation and remodeling around the site of an infection." (PMID 31040245, 2019). "Infection of THP‐1 cells with Mtb leads to increased expression of MMP‐9." (PMID 31199047, 2019). "The mechanism of infection induced MMP-9/TACE expression should be clarified by future experiments." (PMID 30897723, 2019). "In response to infection with Phdp, mmp9 and cox2 expression levels increased from 0 to 4 h." (PMID 30524433, 2018). "MMP9 can also recruit eosinophils and T-cells to the site of infection." (PMID 30544510, 2018). "AMs also secrete elastolytic enzymes, such as MMP-9 in response to irritants and infection." (PMID 28831024, 2017). "However, our analysis, performed on neutrophils at the sites of infection, clearly shows enrichment and active nuclear transcription of mmp9." (PMID 28747644, 2017). "Therefore, NF-kB regulates neutrophil MMP-9 secretion for both direct infection and intercellular networks." (PMID 28173836, 2017). "In the zebrafish model of TB, macrophage migration was central to the dissemination of infection to new sites in an MMP-9–dependent manner, and excessive leukocyte migration may lead to adverse effects in TB, including tissue damage." (PMID 28646039, 2017).
infection (continued). "During leukocytes recruitment into the sites of infection, the leukocytes will migrate through spaces between endothelial cells with the help of pseudopodia and will secrete the proteases like MMP-9 to degrade the basement membrane, which allows the leukocytes to enter into the infected tissue." (PMID 28704922, 2017). "Similarly, we also found an up regulation of tissue remodeling factors induced by extracellular infection with WCH-SK2WT (MMP1, MMP2, and MMP10) and WCH-SK2SCV (MMP1 and MMP9) as well as intracellular infection with WCH-SK2WT (MMP9)." (PMID 28083514, 2016). "We found that MAV-1 infection increased MMP2 and MMP9 activity compared to mock infections." (PMID 27303733, 2016). "Interestingly, in our experiments, MMP9 up regulation was significantly higher in extracellular WCH-SK2WT infection compared to intracellular WCH-SK2WT infection and MMP9 was not significantly induced by intracellular infection with the WCH-SK2SCV variant." (PMID 28083514, 2016). "Moreover, it has been proved that inappropriate activation of MMP-9 at a site of infection can have a profound effect in the tissue destruction of CP." (PMID 27186490, 2016). "In addition to decreased viral burden, lung inflammation and airway resistance was also attenuated in MMP-9 knockout mice compared to MMP-9 competent controls during the acute phase of infection." (PMID 26264019, 2015). "Mmp9-/- mice had reduced neutrophil numbers present in the lung following infection." (PMID 26284919, 2015). "In addition, we observed lower levels of the fibrosis-associated immunopathologic elements MMP-9 and TIMP-1 in the ICOSL KO mice compared to the controls at the advanced stage of infection (16 weeks)." (PMID 25590646, 2015). "Moreover, the invasive ability of sN1 cells was decreased upon infection of cells with MMP9 shRNA (shMMP9, TRCN0000373061) expression virus." (PMID 25823820, 2015). "Our study identifies a pronounced lung MMP9 response at day 1 post infection." (PMID 26284919, 2015). "Gene transcription of Mmp9 was significantly enhanced from 3 days post infection." (PMID 26284919, 2015). "This may account for the observed difference in MMP-9 between infection and L-Omp19 induction since, as we have put forward, lipoproteins are the main components of B. abortus-elicited inflammation." (PMID 23587438, 2013). "Thus either broad MMP inhibition or MMP-9-specific depletion delayed granuloma formation, resulting in impaired macrophage recruitment to the site of infection and reduced granuloma size." (PMID 23420646, 2013). "TIMP-4 levels were lower during the acute phase of infection, persisting as such even when MMP-9 and TIMP-1 have already decreased, until eosinophil meningitis was not definitely recovered, suggesting that TIMP-4 plays a crucial role in the proteolytic balance of BBB damage, in these patients." (PMID 25436884, 2013). "All the probes indicate that mmp9 is up-regulated after infection." (PMID 22720048, 2012). "Using a model wherein a lethal dose of virus mimics many of the characteristics observed after pandemic infections, with greater cytokine/chemokine levels, lung pathology, and inflammatory cells, we showed that MMP9 activity was upregulated in infected lungs, confirming data published recently." (PMID 22496659, 2012). "This indicates afundamentally different innate response to infection between WT andMMP-9−/− mice which may contribute to an atypical fecalmicrobiome in MMP-9−/− mice." (PMID 22694805, 2012). "Furthermore, TNFα induced MMP9 secretion by neutrophils and blocking TNFα in vivo reduced neutrophil recruitment after infection." (PMID 22496659, 2012). "Importantly, MMP9 was functionally required for neutrophil migration into the lung in response to infection and for control of viral replication." (PMID 22496659, 2012). "MMP-9 -/- mice displayed diminished recruitment of leucocytes to the site of infection." (PMID 18700005, 2008).
infection (continued). "Although one study demonstrated that desflurane reduces cancer cell invasiveness by downregulating the Akt–MMP-9 signaling axis, it is unclear whether this effect translates into impaired neutrophil function or delayed tissue repair during postoperative infection." (PMID 41302087, 2025). "Infection with adenovirus encoding shRNA against c-Jun (shc-Jun), but not against p65 (shp65), abolished PARP1 overexpression-induced upregulation of CyclinD1, Pcna, Mmp9, Pxn, Spp1 and Tnc genes, suggesting that c-Jun mediated the effects of PARP1 on VSMC proliferation and migration." (PMID 40744995, 2025). "Similarly, no increase in MMP-9 mRNA was detected in osteoclasts following infection and yet statistically significant increases in MMP-9 protein production were detected following S. aureus challenge and such release was augmented following substance P treatment." (PMID 40056352, 2025). "Finally, the ratio between pro-MMP9/TIMP1 protein levels in the supernatant of S. aureus–stimulated samples was elevated in STAT3-deficient compared with WT BMDM, in particular at 48 h after infection." (PMID 37982695, 2024). "The expression of ToMMP9 was dramatically increased in the skin of the infected/adjacent sites after infection with C. irritans, which suggested that MMP9 might be involved in the response of fish to C. irritans resistance through the innate and the mucosal immunity." (PMID 36833402, 2023). "In addition to P. gingivalis, intravenous infection of hyperlipidemic mice with Aggregatibacter actinomycetemcomitans can promote and accelerate atherosclerotic plaques and time-dependently elevate matrix metalloproteinase-9 (MMP-9) expression." (PMID 35406643, 2022). "Notably, this elevation of MMP-9 is long-term, as MMP-9 is detected three months after infection." (PMID 35563537, 2022). "Moreover, the intensities of Evans blue dye in the Liver, Spleen and Lung of DENV-infected mice were significantly higher than that mock-infected mice or SB-3CT-treated and DENV-infected mice tissues, suggesting that DENV infection induces vascular leakage in mice through promoting MMP-9 production." (PMID 34310658, 2021). "Therefore, the increase of MMP-9 levels could play a role in early detection and in innovative treatment strategies to minimize the consequences of infection and AL in the near future." (PMID 32865714, 2021). "In addition, infection by virulent influenza virus (IV) is characterized by heavy cellular infiltration and severe lung pathology, and both conditions are accompanied by oxidative stress and matrix metallopeptidase 9 (MMP-9) production." (PMID 34209911, 2021). "Our results are in accordance with the literature on response of IL6 family of cytokines and their importance, in addition, we find that matrix metalloproteinase 2 (MMP2) and matrix metalloproteinase 9 (MMP9) with keratan sulfate synthesis pathway may play a key role in the infection." (PMID 32595353, 2020). "Thus, degranulation could contribute to the partial elimination of the ΔyopH mutant observed in tissue infection of the Skap2KO mice, because YopH was sufficient to reduce MMP-9 release from all three receptors tested." (PMID 32392230, 2020). "Matrix metalloproteinase-9 (MMP-9) may play an important role in fighting infection." (PMID 31947787, 2020). "In addition, infection by various flaviviruses can also elevate MMP9 expression." (PMID 32302362, 2020). "Recently, many reports on the MMP-9 function in fishes has also been investigated, and the overexpression of MMP-9 is determined to protect fishes, such as yellow catfish (Pelteobagrus fulvidraco), zebrafish (Danio rerio), and grass carp (Ctenopharyngodon idella) from the infection of pathogens." (PMID 31947787, 2020).
infection (continued). "However, iNOS and MMP9 were amongst the proteins with the highest increased abundance in IECs during infection in both C57BL/6 and C3H/HeN mice, where LXR/RXR appears to be activated, suggesting differences in gene regulation between macrophages and epithelial cells." (PMID 31610608, 2020). "Therefore, our results suggested that CA16 infections result in BBB dysfunction likely through modulating the expression of TJ-associated and AJ-associated proteins, which might be intimately related to MMP9." (PMID 30228270, 2018). "A rapid decline of MMP-9 levels was already evident in the first month of both treatments, suggesting that such therapies may mediate the tissue remodeling and liver inflammation associated with HCV-infection, through their effect on MMP-9 levels." (PMID 27023536, 2016). "As immunohistochemical staining demonstrated, MMP2 and MMP9 expression in atherosclerotic lesions was substantially decreased in mice treated with Ad‐Nkx2‐5, compared to Ad‐EV‐treated controls, and Ad‐shNkx2‐5 infection significant increased the levels of MMP2 and MMP9." (PMID 27993833, 2016). "MMP-9 production is tightly controlled at the level of gene transcription and its unrestricted release/activity may contribute to host tissue damage during infection." (PMID 25931987, 2015). "The ratio of activated MMP-9/latent MMP-9, which indicates the activation of MMP-9 (functional enzyme), was significantly associated with AE-COPD and this association was independent from demographic characteristics of the patients, smoking status, lung function and infections." (PMID 26126526, 2015). "In this mechanism model, the mycobacteria secreted ESAT-6 induced MMP-9 in those epithelial cells neighboring the infected macrophages, which in turn contributed to nascent granuloma maturation and bacterial growth by increasing the recruitment of macrophages to sites of infection." (PMID 22570668, 2012). "In addition to containing MMP9 in preloaded granules, neutrophils are capable of secreting a variety of inflammatory cytokines or chemokines, which could be modulating the MMP9 response after infection indirectly." (PMID 22496659, 2012). "To exclude that the large variation in il1b and mmp9 induction found after immersion might be due to individual variation in responsiveness of different embryos, we decided to compare the immersion system with intravenous infection." (PMID 22003892, 2011). "One could hypothesize that in whole CMPs from preterm deliveries, not only the distal but also the proximal part of the CMP, is rich in leukocytes, MMP-8, MMP-9, and IL-8, thereby reflecting an ascending infection that has overcome the antimicrobial properties of the CMP." (PMID 20868473, 2010). "Furthermore, both induction of the CXCR3 chemokine interferon-gamma-inducible protein-10 (IP-10) and expression of MMP-9 in human lung tissue following ex vivo infection with Chlamydia pneumoniae were previously demonstrated by in situ hybridization in human lung specimens." (PMID 17567922, 2007). "triangularis infection-related proteins, highlighting hub genes such as AKT1, TNF, MMP9, CDK1, and PIK3C3, and enriched pathways in autophagy, immune regulation, oxidative stress responses, and kinase-mediated signaling." (PMID 41993607, 2026). "After infection, Mfsd2a, MMP2 and MMP9 showed significantly up-regulation (P<0.05), while CAV-1 expression was significantly down-regulated (P<0.05), indicating that vesicle transport efficiency or barrier permeability was affected." (PMID 40642060, 2025). "Overall, these data show reduction of MMP-9 and CCL2 concentrations, and an induction of IFN-β and CXCL10 across time, as a result of infection." (PMID 40295794, 2024). "Whilst concentrations of MMP-9 and CCL2 were reduced upon infection, IFN-β and CXCL10 were induced as the infection course progressed, with significant increases over mock after 48 hpi and 72 hpi for both the USUV- and WNV-infected conditions." (PMID 40295794, 2024).